INS (insulin)
Diseases named in the same sentence as INS in open-access papers (continued):
Sharing a sentence is not in itself a finding about the gene and the disease.
cancer (continued). "Insulin and IGF-II also decreased HER3 protein levels in HepG2 and PLC/PRF5 cancer cells but not in Hep3B and Huh7 cells." (PMID 27514687, 2016). "Additionally, as a cancer center, we did not have access to patients' primary care medical records, which might contain more detailed information on glycemic control, including hemoglobin A1c and insulin levels." (PMID 24944108, 2014). "The downregulation of PTPMT1 in pancreatic beta cells has been shown to increase cellular ATP levels and insulin production, however, the generalized role of PTPMT1 in cancer cells has not been characterized." (PMID 23326511, 2013). "Furthermore, some studies included patients who were already on insulin at enrolment, without information on previous exposure; of those who enrolled only insulin-naïve patients, one did not exclude from analysis cases of cancer diagnosed early after the initiation of therapy." (PMID 23209929, 2012). "In mice with cancer cachexia, the PPARγ (PPARG) agonist rosiglitazone, an insulin sensitizer, increases adipose tissue but not muscle mass in late-stage cachexia." (PMID 23781298, 2012). "This cluster predicted cancer mortality, while HOMA-IR and fasting insulin failed to do so." (PMID 38572476, 2024). "Having established that the simultaneous application of insulin and MLN4924 has no impact on cancer cell proliferation, we proceeded to conduct cell migration assays using three types of cancer cell lines (SKOV3, U373, and RCC4) treated with MLN4924 or insulin." (PMID 38272982, 2024). "However, this rescue of STAT3 phosphorylation by insulin, IGF1 and leptin was no longer detectable when the cancer cells were treated with the cholesterol-depleting agent MβCD." (PMID 37907500, 2023). "Evidence suggest that insulin stimulates growth mainly via its own receptor and not the IGF-1 receptor, and that in many cancer cells, the insulin receptor is overexpressed and the A isoform, which has a predominant mitogenic effect, is more represented than the B isoform." (PMID 32854644, 2020). "Besides, Campbell and colleagues reported that metformin users also had reduced cancer compared to non-diabetics (RR 0.94, 95% CI 0.92–0.97) and CVD compared to diabetics receiving non-metformin therapies (HR 0.76, 95% CI 0.66–0.87) or insulin (HR = 0.78, 95% CI 0.73–0.83)." (PMID 33516224, 2021). "However, to our knowledge, this relationship has not been explored in cancer cachexia, and the precise points of EPA interaction within the glucose–insulin-signalling pathway in muscle remains unclear." (PMID 21970879, 2011).
tumor (1,579 papers, 1977 to 2026). "Targeting the Ras–insulin axis has been explored as a strategy to restore metabolic balance, potentially increasing tumor cell susceptibility to therapeutic interventions." (PMID 40906088, 2025). "The SLC30 family, including SLC30A8 (ZnT8) in HCC, regulates zinc homeostasis, which affects insulin secretion and indirectly influences the tumor microenvironment through genetic variants linked to T2DM risk." (PMID 41425581, 2025). "Additional body fat raises the risk for renal cancer through alterations in insulin signaling pathways and by promoting inflammation; both factors encourage tumor growth." (PMID 41041606, 2025). "There were also expression differences between the two primary tumours in ~ 50 insulin/glucose-related genes, such as SLC2A2, which encodes the GLUT2 glucose transporter and PIK3R1, involved in the metabolic actions of insulin." (PMID 40438247, 2025). "These diets not only improve metabolic health but also modulate the tumor microenvironment by reducing inflammation and oxidative stress, which are closely linked to insulin and IGF-1 signaling." (PMID 40428567, 2025). "This is when symptoms begin to appear in many patients due to the neoplastic disorder caused by tumor cells secreting molecules, such as adrenomedullin (AM), which inhibits insulin secretion by β-cells." (PMID 40487412, 2025). "As insulin and insulin‐like growth factors cause tumor progression and metastasis, insulin sensitivity is crucial for preventing cancer cachexia and tumor recurrence." (PMID 40385349, 2025). "In hepatocytes and tumor cells alike, metformin reduces hepatic gluconeogenesis and systemic insulin levels, thereby blunting the insulin/IGF-1 signaling cascade implicated in tumorigenesis." (PMID 41010968, 2025). "The study will quantify pathway activation and assess its association with tumor stage, overall survival, and metabolic parameters, including the requirement for oral antidiabetic agents, insulin therapy, and hemoglobin A1c levels." (PMID 41397158, 2025). "Secondary endpoints consist of the evaluation of overall survival, defined as the time of the first study treatment to death from any cause, modification in insulin levels, and changes in tumor glucose uptake values, measured by FDG-PET/DCE MRI." (PMID 39338183, 2024). "In contrast, pre-TKI statin use (HR, 1.28; 95% CI, 1.10–1.49; p = 0.002) and insulin use increased the risk of tumor progression." (PMID 38254739, 2024). "For PFS, only post-TKI statin use was beneficial (HR, 0.36; 95% CI, 0.17–0.77; p = 0.009) with age >60 years, but insulin use remained a risk factor for tumor progression." (PMID 38254739, 2024). "Elevated adiposity and altered IGF-1 levels are also linked with OC, where insulin’s tumor-enhancing effects often activate the PI3K/Akt-mTOR pathway, a key regulator of cell growth, proliferation, and survival." (PMID 39596005, 2024). "This similarity is evidenced by the shared physiological functions of the receptors, such as in tumor-associated hypoglycemia caused by elevated levels of insulin or IGF-2 from tumor cells." (PMID 39273251, 2024). "Insulin-producing tumors exhibited smaller size, lower grade, and lower tumor-mutation burden, consistent with their generally more beneficial prognosis." (PMID 39456803, 2024). "An alternative explanation is that a decrease in insulin levels caused by low glucose slows tumor growth." (PMID 39574543, 2024). "The lack of GLP-1R expression was associated with impaired overall survival, larger tumour diameter, higher Ki-67 PI and weaker insulin staining." (PMID 37894845, 2023). "Preclinical studies have implicated insulin in tumor promotion by either directly or indirectly affecting epithelial tissues with the help of IGFs." (PMID 37373357, 2023). "The endocrine function of myokines is implicated in body weight regulation, inflammation, insulin sensitivity, suppression of tumour growth and improvement of cognitive function." (PMID 37462619, 2023).
tumor (continued). "The differences in response to insulin between the genotypes were associated with differences in maximum diameter of the tumor, and hepatic accumulation of DCA." (PMID 37852976, 2023). "Secondly, tumour secreted ImpL2 causes a reduction in muscle insulin signalling, which contributes towards reduced translation and increased muscle atrophy." (PMID 38014610, 2023). "Anthropometric measures, such as visceral fat, and metabolic measures, such as fasting insulin, were biological mediators of the association between exercise and reductions in circulating tumor cells." (PMID 38148846, 2023). "Increased cytokine release caused by a tumor macroenvironment will cause local/systemic inflammation and lead to insulin resistance, B cell dysfunction, and insulin autonomy." (PMID 36769405, 2023). "Glucagon-like peptide (GLP)-1 and its receptor have also been implicated in the insulin metabolism that plays a dominant role in cell and tumor growth." (PMID 35910464, 2022). "Second, the mutational signature of tumors responsive to dapagliflozin – that is, those with mutations upstream of canonical insulin signaling – argues against a direct effect of dapagliflozin on the tumor." (PMID 35595952, 2022). "Insulin directly stimulates tumor-associated fibroblasts (TAF) through activating the IRS-PI3K-AKT-mTOR signaling pathway and inactivating the FoxO1 signal pathway." (PMID 35252207, 2022). "Restricting food intake to designated time windows has been shown to dramatically reduce serum growth hormone, leptin, and insulin, increasing insulin sensitivity three-fold and selectively rendering tumor cells more susceptible to cytotoxic therapies." (PMID 35163264, 2022). "This adipokine imbalance is closely associated with insulin resistance, lipolysis and pro-inflammatory signaling pathways, contributing to a favorable microenvironment for tumor growth and progression." (PMID 36292657, 2022). "For NODM patients, insulin use or high insulin receptor expression in tumor cells is associated with higher malignancy rates in pancreatic precursor lesions." (PMID 35252207, 2022). "In this case, treatment of mice with insulin improves the cardiomyopathy associated with these models and decreases tumor growth." (PMID 35406791, 2022). "Medical therapy for patients with neuroendocrine neoplasms (NEN), including insulin-producing ones, is aimed at decreasing the circulating hormones which cause typical syndromes and control of tumor growth." (PMID 35838801, 2022). "Chronic inflammation, excess insulin secretion and the hyperactivation of growth pathways are closely associated with tumor development and progression." (PMID 36292657, 2022). "Various in vitro and clinical studies have associated elevated circulating insulin levels with tumour growth and increased cell proliferation." (PMID 35610365, 2022). "The effect of PI3Kγ ablation on reduced tumour growth was explained by reduced tumour cell proliferation, which was associated with reduced insulin levels, liver lipids, and reduced expression of tumour-promoting cytokines." (PMID 34704005, 2021). "Restoration of insulin signaling in neurons prevents tumor progression and rescues the lethality caused by GB in Drosophila models." (PMID 33526430, 2021). "Adiponectin also exhibits strong insulin sensitizing and balancing activity, and reduced adiponectin levels enhance insulin signalling associated with neoplasia." (PMID 34485137, 2021). "We further observe a regulatory role of the molecule in pathways associated with PDAC ECM remodeling and tumor-stromal crosstalk, such as INS/IGF-1, RAS/MAPK, laminin interactions and collagen biosynthesis." (PMID 32660466, 2020). "In parallel, leisure-time physical activity is associated with conceivable anti-tumor effects through sympathetic activation, reduced endocrine factors (sex hormones, insulin, and myokines), and improved immune function." (PMID 33117814, 2020).
tumor (continued). "For example, words such as risk, weight, gain, tumor, insulin, metabol, and disease can be interpreted as describing health-related issues associated with sugar consumption, including increased adiposity and metabolic related diseases." (PMID 33870042, 2020). "Excessive consumption of ketogenic diets, however, can provoke tumor growth by causing insulin insensitivity and glucose elevation." (PMID 32219096, 2020). "Non-islet-cell-tumor-induced hypoglycemia (NICTH) is caused on rare occasions by secretion of insulin from tumor cells that are reported to have a single tissue origin." (PMID 29166433, 2019). "Such IR is characterized by diminished responsiveness of muscle and fat tissues to the insulin-controlled glucose uptake that is usually associated with a compensatory rise of insulin pancreatic production and its release into the blood in tumor-bearing hosts." (PMID 31019893, 2019). "The possible cause is the high concentration of leptin, insulin, insulin-like growth factor-I and low of adiponectin, which together, are likely to promote tumor growth and progression." (PMID 31185699, 2019). "While loss of PTEN leads to improved insulin sensitivity, this metabolic effect has been credited for the tumor suppressing functions of PTEN." (PMID 30038596, 2018). "Chronic adaptation to the aerobic exercise training decreased tumor weight, cachexia and metastasis and were associated with low glucose and insulin levels and high insulin sensitivity before and after tumor cell inoculation." (PMID 29867528, 2018). "Both increased levels of insulin and glucose have been associated with tumor growth and poor overall prognosis in different cancer types." (PMID 29423103, 2018). "Spearman analysis was performed to test the associations between the tumor size and insulin, C-peptide, and glucose levels." (PMID 30522468, 2018). "The signaling pathway induced by EGF or insulin are also associated with tumor cell proliferation and migration." (PMID 29020972, 2017). "We reasoned that transcriptome analysis would shed light on the cause for the differences in tumor latency time by chronic insulin analogue treatment." (PMID 28173837, 2017). "The tumor burden was associated with circulating cholesterol, triglyceride, glucose, insulin, leptin and adiponectin concentrations." (PMID 26959117, 2016). "Sporadic, partial loss of CYR61 or insulin expression was found in rare tumor regions, possibly due to de-differentiation during tumor progression (not shown)." (PMID 26625209, 2016). "Insulin-positive cells were associated with the tumor, and cells positive for both GFP and insulin were also present at very low levels (arrows)." (PMID 26192435, 2015). "HIF1α can also be activated by nitric oxide, cytokines, insulin growth factors, expression of oncogenes, or mutation to tumor suppressors." (PMID 24489651, 2014). "On the other hand, the mice group on CRD exhibited the least tumor burden associated with a significant reduction in levels of insulin, IGF-1, leptin, MCP-1, VEGF and IL-6." (PMID 25026276, 2014). "Comparing the CRD and RD groups, it can be suggested that the main tumor regressive effects of CRD are associated with decreased production of insulin, IGF-1 and leptin." (PMID 25026276, 2014). "By staining each of the PDICs that had been previously identified by their loss of insulin, we determined that tumor cells in all PDICs were positive for Id1." (PMID 23691228, 2013). "We have also recently reported that insulin regulates the expression of novel gene transcripts/splice variants in tumour tissue." (PMID 23573093, 2013). "Women in the highest quartile of insulin had a twofold increase in the risk of tumor recurrence and a threefold increase in risk of death versus those patients in the lowest quartile." (PMID 23050155, 2012).
tumor (continued). "Insulin deficiency or insulin blocking reduces tumor incidence or progression and is reversible with re-introduction of insulin." (PMID 22853725, 2012). "The PTEN tumour suppressor encodes a phosphatase, and its daf-18 orthologue in Caenorhabditis elegans negatively regulates the insulin/IGF-1 DAF-2 receptor pathway that influences lifespan in worms and other species." (PMID 18836529, 2008). "The leucine-rich diet prevented the decrease in plasma insulin level associated with tumour growth in the WL group (L = 6.216 ± 0.872 ng.mL-1; WL = 3.547 ± 0.286*; PL = 5.019 ± 0.552; *p < 0.05 compared to C and P)." (PMID 17341295, 2007). "Prolonged culture of 2 tumours for up to 16 days was associated with the gradual decline of insulin release to a steady output of 2-15 ng 24 h-1." (PMID 2825749, 1987). "Insulin can cause cell proliferation and tumor growth because it is known to induce cell division." (PMID 40923112, 2025). "Interestingly, pathways related to normal pancreatic function, such as insulin signaling and resistance, were also significantly enriched, highlighting the broad biological disruption caused by the tumor." (PMID 40869429, 2025). "Elevated insulin levels may generate hydrogen peroxide, inducing oxidative stress and exacerbating damage through mutations in tumor-related genes." (PMID 40212965, 2025). "Previous studies have suggested that dysfunction in insulin regulation and secretion may not only precede tumor development but could also occur as a direct consequence of tumor growth, complicating causal interpretation." (PMID 41573197, 2025). "Chronically elevated levels of insulin and IGFs may contribute to increased cell division and tumor growth in the liver, increasing the risk of HCC development." (PMID 38666802, 2024). "The mechanisms underlying NICTH may involve tumor secretion of insulin, replacement of hepatic tissue, increased glucose utilization by the tumor, or, most commonly, secretion of IGF-2." (PMID 38868260, 2024). "Additionally, insulin signaling is associated with regulation of cancer-associated fibroblasts (CAFs) in the tumor microenvironment to further promote tumor growth and progression." (PMID 38952983, 2024). "Surprisingly, we found that the knockdown of ImpL2 in the tumour (RasV12, dlg1RNAi) caused a reduction in fat body pMad staining, suggesting that there may be signalling crosstalk between the insulin/PI3K and TGF‐β pathways in the fat body." (PMID 38014610, 2023). "Increased insulin levels may affect TC risk, which is mediated by insulin receptors overexpressed in tumor cells and tissues." (PMID 38004062, 2023). "Additionally, compared to normoxia, hypoxic tumor exosomes improved oxidative phosphorylation in macrophages derived from bone marrow via the transfer of let-7a miRNA, causing inhibition of the insulin-Akt-mTOR signaling pathway." (PMID 36233088, 2022). "However, the architecture of autophagy-deficient, tumor-free pancreata was effaced, normal acinar tissue was largely replaced with low-grade pancreatic intraepithelial neoplasias (PanINs) and insulin expressing islet β-cells were reduced." (PMID 35372352, 2022). "Findings of these experiments suggest that SIRT6 by targeting the inhibitor WNT4 might modulate insulin secretion from pancreatic β‐cells and thereby probably curtail muscle atrophy associated with tumour growth in Tu‐Sk.T6Tg mice." (PMID 34212132, 2021). "A pivotal cause for the enhancement of ET anti-tumor activity by fasting or FMD appears to be the reduction in blood insulin, IGF1 and leptin, with the consequent inhibition of the PI3K–AKT–mTOR pathway, at least in part through the upregulation of EGR1 and PTEN." (PMID 34322508, 2021). "Recent work using the Drosophila model has provided important insights into novel facets of conserved Tribbles functions in stem cell quiescence, tissue regeneration, metabolism connected to insulin signaling, and tumor formation linked to the Hippo signaling pathway." (PMID 33672471, 2021).